ZNF526 (zinc finger protein 526)
Description:
Probable transcription factor.
Synonyms: KIAA1951; MGC4267; DENNED
Tractability: PROTAC: ubiquitination databases record sites on it.
Gene: Protein-coding gene on chromosome 19 (42,216,774 to 42,228,201, forward strand). Ensembl gene ENSG00000167625.
Subcellular location: Nucleus
Subcellular location (Human Protein Atlas): Golgi apparatus; Nucleoplasm; Vesicles
Gene Ontology:
Molecular function: protein binding
Cellular component: nucleus
Genetic constraint (gnomAD): Loss-of-function variants: 18 observed, 41.39 expected, observed/expected ratio (o/e) 0.43, 90% interval 0.3 to 0.64. The upper end of that interval is the gene's LOEUF score, 0.64, which puts it in group 2 of 6, group 1 being the genes least tolerant of losing a copy. Missense variants: 838 observed, 954.07 expected, observed/expected ratio (o/e) 0.88, 90% interval 0.83 to 0.93. Synonymous variants: 355 observed, 380.7 expected, observed/expected ratio (o/e) 0.93, 90% interval 0.85 to 1.02.
Homologues: Orthologues: macaque ZNF526 (99% identical), dog ZNF526 (89% identical), rabbit ZNF526 (89% identical), pig ZNF526 (88% identical), mouse Zfp526 (87% identical), rat Zfp526 (87% identical), guinea pig ZNF526 (86% identical), tropical clawed frog znf526 (43% identical), zebrafish znf526 (41% identical). Paralogues in human: ZNF574 (36% identical), ZNF91 (19% identical), ZNF160 (18% identical), ZNF594 (18% identical), ZNF208 (18% identical), ZNF84 (18% identical), ZNF142 (17% identical), ZNF473 (17% identical), ZNF420 (17% identical), ZNF569 (17% identical), ZNF107 (17% identical), ZNF99 (17% identical), and 24 more.
Diseases named in the same sentence as ZNF526 in open-access papers:
ZNF526 is named in the same sentence as 3 diseases in open-access papers, as found by Europe PMC text mining. Sharing a sentence is not in itself a finding about the gene and the disease. The quoted sentences say what the papers report.
microcephaly (1 paper, 2022). A congenital or acquired developmental disorder in which the circumference of the head is smaller than normal for the person's age and sex. "Moreover, the ZNF526 biallelic variants affect eyes and brains in a neurodevelopmental disorder that leads to severe microcephaly." (PMID 35041720, 2022).
ZNF526 also shares sentences with these, for which no sentence is quoted: neurodevelopmental disorder (1 paper); primordial dwarfism (1).